PLK3 (polo like kinase 3)
Diseases named in the same sentence as PLK3 in open-access papers (continued):
Sharing a sentence is not in itself a finding about the gene and the disease.
cancer (continued). "Despite being known for its potential among other PLK types (PLK2, PLK3, PLK4, and PLK5), PLK1 is determined recently as a potential oncogenic target across various cancer types due to its extensive research exploration and essential mitotic roles." (PMID 41404416, 2025). "Knockdown of PLK3 inhibited expression of MMP11 and SNAI2, known players in the regulation of cancer invasion and metastasis." (PMID 38169509, 2024). "Among these APAs, 5 APAs (INTS4, SLC27A3, BCCIP, PLK3, HR) were differentially expressed in CRC tissues, when compared with para-cancer tissues." (PMID 35487956, 2022). "Although the beta-carboline compounds can inhibit the kinase activity of PLK1, PLK2 and PLK3, it is likely that the inhibition of PLK1 contributes to toxicity of these compounds to cancer cells." (PMID 23056340, 2012). "There are currently no specific ALDH1A1 and PLK3 inhibitors available for clinical cancer treatment." (PMID 38169509, 2024). "Furthermore, the reduced Plk3 expression in PDAC from the Segara and Logsdon cancer microarray datasets in the Oncomine database also supports our findings." (PMID 38605037, 2024). "Overexpression of PLK3 may deplete PTEN levels, resulting in the inhibition of apoptosis and, ultimately, cancer progression." (PMID 34638440, 2021). "Two genes PLK3 and USP39 were not covered by any representative term and none of them is an NCG cancer gene." (PMID 34504716, 2021).
infection (2 papers, 2023 to 2025). The state of being infected such as from the introduction of a foreign agent such as serum, vaccine, antigenic substance or organism. "To further investigate the role of PLK3 in GBM growth, we overexpressed Plk3 in the GL261 cell line by lentiviral infection." (PMID 39866232, 2025).
PLK3 also shares sentences with these, for which no sentence is quoted: basal cell carcinoma (1 paper); bladder cancer (1); cervical squamous cell carcinoma (1); chronic myeloid leukaemia (1); endometrial cancer (1); Fanconi anemia (1); head and neck tumors (1); hypothyroidism (1); kidney cancer (1); leukaemia (1); malignant glioma (1); neurodegenerative disease (1); oligoastrocytoma (1); oligodendroglioma (1); parasite infection (1); Renal Dysfunction (1); seminoma (1); synucleinopathies (1); tendinopathy (1).